IL22 (interleukin 22)
Diseases named in the same sentence as IL22 in open-access papers (continued):
Sharing a sentence is not in itself a finding about the gene and the disease.
tumor (continued). "Th17 cells are a veritable cytokine factory, producing a range of cytokines and chemokines, including IL-17A, IL-17F, IL-21, IL-22, TNF-α, and CCL20, which modulate the behavior of fibroblasts, endothelial cells, epithelial cells, macrophages, and tumor cells, thereby sculpting the TME." (PMID 39906741, 2024). "Tumor-specific upregulation of cytokines produced by Th17 CD4+ cells, such as IL-17A and IL-22, has been observed in human CRC, and studies in mouse models of spontaneous intestinal tumorigenesis have demonstrated the importance of these cytokines in tumor progression." (PMID 38096329, 2023). "Previous studies reported that pro-inflammatory cytokines, such as IL-1β, IL-6, IL-17, and IL-22, in the blood reduced significantly and were observed in a CRC patient trial with consumption of 6-month probiotics (IL-1 is required for tumor invasiveness and angiogenesis)." (PMID 37200915, 2023). "IL-17 and IL-22 production from NKT17 cells and IL-17 production from MAIT cells have also been shown to contribute to tumour growth and metastasis, with a recent single cell analysis of tumour-infiltrating T cells across 21 cancer types showing that 50% of intratumoural Tc17 cells were MAIT cells." (PMID 37536148, 2023). "Although IL-22+ ILC3 were shown to have an important role in cancer, the contribution of ILC3-derived IL-22 to tumor angiogenesis has not been elucidated yet." (PMID 37234993, 2023). "IL-22 is increased in the tumor of patients with non-small cell lung cancer (NSCLC), pancreatic cancer, gastric cancer and hepatocellular carcinoma and predicts a poor prognosis, higher disease stage, and faster tumor progression." (PMID 37529610, 2023). "Apart from this particular case, since IL-22 has mainly tumor-promoting properties, there are no other relevant applications of Th22 cells in adoptive cell therapy." (PMID 36980536, 2023). "Our results indicate that IL17+ cells may promote tumor progression through IL17, IL22, and IL26 signaling, highlighting the possibility of targeting IL17+ cells and associated signaling pathways as a therapeutic strategy to treat GC." (PMID 35999201, 2022). "Interestingly, we found their receptors, IL17RA/IL17RC for IL17A/IL17F, IL10RB/IL22RA1 for IL22, and IL20RA/IL10RB for IL26, were upregulated in tumor cell than in normal epithelial cells." (PMID 35999201, 2022). "Although γδ T cells were able to produce IL-17 and IL-22, the absence of IL-17–IL-17R reduced tumor-specific T cell responses elicited by chemotherapy-induced tumor cell death." (PMID 36499125, 2022). "Among these, IL-22 mainly stimulates the downstream target gene expression through the JAK/STAT pathway, such as cell cycle control and antiapoptotic genes, and promotes tumor proliferation and metastasis." (PMID 35669104, 2022). "IL-22 has been demonstrated the function of promoting tumor progression through mediating the target expression of IL22R in stem cells, and inducing the proliferation to enhance tumor growth." (PMID 34941188, 2021). "Although IL-22 likely possesses other cellular targets other than tumor cells, these have not been discovered so far." (PMID 33851257, 2021). "IL22RA1 is a receptor of interleukin 22, has been reported working as a signal transducer and activator of STAT3 signaling in the malignant transformation, it plays an important role in promoting tumor growth and metastasis and inhibiting cell apoptosis." (PMID 34040139, 2021). "Altogether, ILC cells including NK cells could contribute to the increased level of TNF-alpha, GM-CSF, IFN-gamma, IL-4, IL-5, IL-13, IL-17, and IL-22, modulating TME and contributing to tumor progression or antitumor activities." (PMID 35008550, 2021). "The increase of IL-21 mRNA in tumor tissue at the G1 stage may indicate that there are still efficient mechanisms aimed at limiting its growth, which is also reflected in the IL21/IL22 mRNA ratio value." (PMID 34300224, 2021).
tumor (continued). "It is mainly because IL22 could induce the expression of MUC1, allowing CAR‐T cells to bind more accurately to tumor cells." (PMID 31800160, 2020). "IL-1β and IL-23 increased levels of IL-22 mRNA and IL-22-producing ILC3 in 4T1 tumor." (PMID 32649314, 2020). "Tumor-infiltrating T, B, and NK cell levels and plasma concentrations of Th1 (IL-2, IFN-γ, and TNF-α), Th2 (IL-4, IL-5, IL-6, and IL-10), Th9 (IL-9), and Th17 (IL-17A, IL-17F, IL-21, and IL-22) cytokines were evaluated." (PMID 32802733, 2020). "Administration of recombinant IL‐22 in the TME does not influence in vivo tumor initiation and proliferation but only promotes malignant transformation of cancer cells." (PMID 31725949, 2020). "Similarly the infiltration of cellular sources of IL-22 including Th22 and CD4+ T cells in the intratumoral tissue increases, corresponding to the stage of tumor." (PMID 33042126, 2020). "Tumor development was dependent on ILC3s but IL-22 and IL-17 do not seem to be involved in the process." (PMID 31024531, 2019). "IL-9 at D3 and D7 seemed to be related to anti-tumor effect and IL-6 at D7 and D60, and IL-22 at D60 was related to regenerative but not pro- or anti- inflammatory function." (PMID 31751357, 2019). "Compared to the primary tumor, recurrent NSCLC had higher levels of IL-22 expression." (PMID 31750252, 2019). "Our results demonstrate that IL-24, but not IL-22, is required for the skin reaction induced by PPD application." (PMID 30755657, 2019). "IL-22 exerted no influence on tumor growth (volume, 546.53 mm3; weight, 246.26 mg) when compared with vehicle (volume, 596.28 mm3; weight, 281.96 mg, P > 0.05)." (PMID 31750252, 2019). "Furthermore, both IL-22 and its functional transmembrane receptor (IL-22R1) have been found to be significantly expressed in CRC epithelial and tumor stromal cells." (PMID 31637216, 2019). "These experiments indicate that CARD9 signaling in the immune environment of developing colorectal cancers can trigger the tumor-promoting STAT3 pathway within tumor cells, presumably via ILC-mediated IL-22 production, comparable to its role during epithelial regeneration after acute colitis." (PMID 30906296, 2019). "The Th17 cytokines IL-17 and IL-22 promote proliferation and migration in vitro and tumor growth in vivo of human non-melanoma skin cancers." (PMID 30559930, 2018). "IL-22 expression and RORγt/AhR mRNA in BALF was also remarkably increased in tumor site." (PMID 30473538, 2018). "Once tumor were established, mice were subjected or not to subcutaneous injections of IL-22 once a day for 7 days, in presence of peptide vehicle, Ctrl1 or KIRESS peptides." (PMID 28445952, 2017). "IL-17 and IL-22 enhances IL-23 protumourigenic activity which enhance tumour growth and survival through JAK/STAT3 by activation of IL-6 results in cellular proliferation, angiogenesis, and tumour progression." (PMID 28275390, 2017). "Although further work elucidating the role of IL-22 in SCC proliferation and invasion is warranted, our study sheds light upon the possible role of IL-22 in tumorigenesis in vivo and provides important information about tumor immunity in transplant recipients." (PMID 23667456, 2013). "Since TH17 cells may act to promote HCC pathogenesis via production of IL-17 and IL-22; if we can modulate the TH17 status in the body, it may be possible to affect tumor progression." (PMID 23316374, 2012). "Hence we analyzed the secretion of IL-22, TNF-α and IFN-γ, each of which is known to contribute to certain forms of skin pathogenesis." (PMID 23056446, 2012). "In tumor-bearing eyes, IL-17 transcripts, but not IL-22 transcripts, were detected, and the expression of IL-21 was significantly higher than in the controls." (PMID 21949734, 2011). "Neither IL-17 nor IL-21 and IL-22 were detected in significant quantities in A20.IIA-GFP tumor cells." (PMID 21949734, 2011).
tumor (continued). "We also showed that IL-22 did not enhance the anti-tumor immunity effectively in vivo by increasing the expression of IFN-α and TNF-α in A498 cell xenografts." (PMID 21625390, 2011). "However, Th22 cells also showed enhanced capacity to produce IL-22 and IL-13 in EOCRC, which could promote aggressive tumor behavior and shape an immunosuppressive environment favorable to tumor survival and growth." (PMID 41425582, 2025). "Moreover, Th9/Th22 correlation was negative in EOCRC cohort, suggesting that IL-9-driven inflammatory signals may help restrain IL-22-mediated STAT3 activation and tumor-promoting self-renewal pathways." (PMID 41425582, 2025). "Similarly to IL-21, no statistical differences in the IL-22 serum levels were observed when considering the grade of malignancy (p = 0.931) and the biological type of the tumour (p = 0.601)." (PMID 40729006, 2025). "However, when IL-22-producing Th17, NKT, and Th22 cells infiltrate into the tumor, the increased amount of IL-22 can possibly offset the effect of BTN2A1 and Vγ9Vδ2 T cells, which eventually leads to tumor progression." (PMID 39769218, 2024). "In this paper, we aim to integrate our previous findings regarding IL-22-mediated hepatocyte proliferation and HCC progression to further describe an approach that could be utilized to balance simultaneous liver regeneration and suppressed tumor progression." (PMID 38533053, 2024). "Tumor formation is unquestionably a multifactorial process and IL‐22 alone certainly is not responsible for this process, but without appropriate regulation it may enhance tumorigenesis by initiating excessive epithelial cell proliferation." (PMID 38363052, 2024). "Tc17 cells may stimulate tumor development via IL-17, IL-22, and IL-26, while non-cytotoxic Tc17 cells may become cytotoxic in the presence of IL-12, having a deadly impact on tumor cells." (PMID 39676857, 2024). "In addition to this, IL-22 was found to increase the efficacy of the CAR-T cells by upregulating the proportion of central memory and effective memory T cells, allowing T cell proliferation, longer survival and effective killing of tumour cells." (PMID 39935547, 2023). "Type II inflammation, mediated by IL-11, IL-22, IL-33, IL-6/membrane IL-6 receptor α (mIL-6 Rα) and cell-mediated immune response through CD4+ Th2 cells, which produce IL-12, M2 macrophages, and group 2 innate lymphoid cells (ILC-2), induces classic anti-inflammatory signaling and tumor relapse." (PMID 37296983, 2023). "Furthermore, IL-22 not only antagonized the apoptosis inducing and cell cycle arresting effect by chemotherapy and molecular targeted drugs on NSCLC cell lines but also promoted tumor cell proliferation and tumor tissue growth." (PMID 35669104, 2022). "Thus, we hypothesized that IL17+ T cells in GC could promote tumor growth via IL17, IL22, and IL26 signaling." (PMID 35999201, 2022). "As expected, mice lacking the receptor for IL-22, IL-22RA1, were protected from tumor development." (PMID 36551508, 2022). "Moreover, the role of the ILC3 producing IL-22 in promoting rather than controlling tumor progression is also still uncertain." (PMID 33467134, 2021). "Interestingly, IL-5, IL-7, IL-20, and IL-22, rather than their receptors, have been widely reported to have the ability to predict tumor prognosis." (PMID 34497605, 2021). "However, the role of TGF-β for the emergence of IL-17A+IL-22-, IL-17A+IL-22+, and IL-17-IL-22+ CD4+ T cells in the tumor microenvironment remained unknown and was addressed by our study." (PMID 32451418, 2020). "Tumor tissue expressed higher level of IL-22 mRNA than that in normal mammary tissue." (PMID 32649314, 2020). "However, this inactivation of IL‐22 gene did not affect the initiation and hyperplasia stages of tumor progression in IL‐22−/−PyMT mice." (PMID 31725949, 2020). "Whether the presence of IL-22 is important at an early stage for the development of tumours, or for maintaining tumour progression, is not yet clearly established." (PMID 31770366, 2019).
tumor (continued). "However, IL-22 was previously demonstrated as a tumor promoting or negative prognostic factor in patients with HCC." (PMID 30824840, 2019). "Expression of IL-22 in primary tissue may arise from non-tumor cells or from the interaction between tumor and non-tumor cells and stroma." (PMID 31750252, 2019). "Hence, our data show that ALCL is a tumor that is dependent on TYK2 for cell survival, that TYK2 is activated through an autocrine loop involving IL-10 and IL-22, and that TYK2 promotes cell survival at least in part through activating the expression of the BCL2 family protein, MCL1." (PMID 30131584, 2019). "Interestingly, IL-22 production and IL-22/AhR mRNA was significantly elevated in lung-resident CD4+ T cells from tumor site in comparison with those from nontumor site (all P<0.0001)." (PMID 30473538, 2018). "Indeed, tumor cells can develop resistance mechanisms that favour cancer growth, and the compromised expression of SOCS3 in response to IL-22 might be representative of this situation." (PMID 28445952, 2017). "One study has proposed that IL-22 is expressed by the tumor cells themselves; however, an earlier study from our group was not able to confirm these results, supporting the notion that IL-22 is expressed in the environment but not in the tumor cells themselves." (PMID 27388918, 2016). "These pro-tumorigenic cytokines include interleukin (IL)-6, IL-11, IL-21 and IL-22 that activate the STAT3 transcription factor; TNFα, IL-1 and IL-18 that activate NF-κB; and the IL-23 to IL-17 axis of inflammation that activates both STAT3 and NF-κB in tumor cells." (PMID 31051015, 2016). "In the AOM/DSS-induced murine CAC model, Th17-related cytokines, including IL-17A, IL-21, IL-22, TNF-α, and IL-6, are produced by tumor-infiltrating lymphocytes (TIL), which could activate the STAT3/NF-κB pathway, thereby promoting CAC cell proliferation and accelerating tumor progression." (PMID 40109347, 2025). "In addition, the expression of several pro-inflammatory cytokines and chemokines such as IL-1β, IL-22, TNF-α, CXCL1, CXCL2, CCL17 and CCL20 were reduced in IL-38KO mice, suggesting that IL-38 promotes tumour growth and development in cSSC through promoting an inflammatory tumour environment." (PMID 40057603, 2025). "Therefore, blocking Steap4 in addition to supplementation with IL-22 could be a potential treatment regime to boost liver regeneration without triggering tumor progression after PVL." (PMID 38533053, 2024). "Thus, a combination of IL-22 supplementation and Steap4 blockade could potentially be applied as a novel therapeutic approach to boost liver regeneration without facilitating tumor progression after PVL." (PMID 38533053, 2024). "Additionally, IL-22 levels were significantly higher in CRC tissues than adjacent noncancerous tissues, suggesting that IL-22 is abnormally expressed during CRC development and may be associated with tumor proliferation and invasion." (PMID 39073546, 2024). "Moreover, a combination of IL-22 supplementation and Steap4 blockade could possibly serve as a novel therapeutic approach to boost liver regeneration without facilitating tumor progression after PVL." (PMID 38533053, 2024). "Given the increase in production of IL‐1β, TNF‐α, IL‐12, IL‐22, and IL‐6 by the expanded inflammatory Ly6C+MHCII+ monocyte population in the tumor following the administration of SL7207, it was hypothesized that monocyte populations may underpin the tumor‐growth inhibition effects of SL7207." (PMID 34633664, 2021). "Importantly, IL17 and IL23 alongside IL22 and cell-autonomous acting IL21, all promote and stabilize the Th17 phenotype and sustain inflammation through various Stat3-dependent feed-forward loops within the tumour, stromal and haematopoietic cells of the microenvironment." (PMID 20478049, 2010).
tumor (continued). "The cytotoxic effect of gefitinib with or without IL-22 was further examined by Ki67 (a biomarker of tumor proliferation) and TUNEL staining analysis (evaluation of tumor apoptosis)." (PMID 31750252, 2019). "GSI stimulation led to the reduction in IL-22 secretion by CD4+ T cells purified from both nontumor site (135.2 ± 24.02 compared with 117.8 ± 16.40 pg/ml, P=0.041) and tumor site (264.3 ± 79.76 compared with 168.1 ± 68.41 pg/ml, P=0.003)." (PMID 30473538, 2018). "We found that IL-22 significantly induced mRNA and protein expression of SOCS3 in healthy keratinocytes, but not in SCC or BCC tumor cells." (PMID 28445952, 2017). "Namely, multiple cytokines that promote the M1-to-M2 switch (including IL-5, IL-10, IL-17, IL-22) were higher in the serum of PyMT-bearing mice independent of the presence and absence of TAC, indicating the involvement of tumor properties in inducing this switch." (PMID 37508517, 2023). "Of note, non-suppressive tumor-infiltrating CD56bright ILCs were distinguished from regulatory CD56+ ILCs by a different gene expression profile and high production of IFNγ and TNFα in the absence of IL-22." (PMID 30454038, 2018). "Similarly, IL-22 mRNA expression was also decreased in response to GSI treatment in CD4+ T cells from nontumor and tumor sites (P<0.0001)." (PMID 30473538, 2018). "In the present study, the absence of STAT1 significantly increased the production of Th17 cytokines (IL-17A, IL-17F, and IL-22) but not of TNF-α and IFN-γ, indicating that a lack of STAT1 signaling induces a significant change in the microenvironment that supports inflammation and tumor formation." (PMID 30235866, 2018).